TSGA10 (testis specific 10)
Description:
Plays a role in spermatogenesis. When overexpressed, prevents nuclear localization of HIF1A (By similarity).
Synonyms: CEP4L; CT79; SPGF26
Tractability: No criterion of Open Targets' tractability assessment is met for any kind of drug.
Gene: Protein-coding gene on chromosome 2 (98,995,156 to 99,154,964, reverse strand). Ensembl gene ENSG00000135951.
Subcellular location: Cytoplasm; Cytoplasm, cytoskeleton, microtubule organizing center, centrosome, centriole
Subcellular location (Human Protein Atlas): Flagellar centriole
Gene Ontology:
Molecular function: protein binding
Biological process: spermatogenesis
Cellular component: centriole; cytoplasm; motile cilium; neuron projection; sperm fibrous sheath; sperm principal piece
Genetic constraint (gnomAD): Loss-of-function variants: 34 observed, 75.65 expected, observed/expected ratio (o/e) 0.45, 90% interval 0.34 to 0.6. The upper end of that interval is the gene's LOEUF score, 0.6, which puts it in group 2 of 6, group 1 being the genes least tolerant of losing a copy. Missense variants: 577 observed, 728.49 expected, observed/expected ratio (o/e) 0.79, 90% interval 0.74 to 0.85. Synonymous variants: 194 observed, 237.62 expected, observed/expected ratio (o/e) 0.82, 90% interval 0.73 to 0.92.
Homologues: Orthologues: chimpanzee TSGA10 (99% identical), macaque TSGA10 (98% identical), rabbit TSGA10 (97% identical), dog TSGA10 (96% identical), rat Tsga10 (96% identical), mouse Tsga10 (95% identical), pig TSGA10 (95% identical), guinea pig TSGA10 (94% identical), tropical clawed frog tsga10 (50% identical), zebrafish tsga10 (43% identical). Paralogues in human: CEP135 (38% identical), CROCC (21% identical), CEP250 (19% identical), CROCC2 (15% identical).
Diseases named in the same sentence as TSGA10 in open-access papers:
TSGA10 is named in the same sentence as 28 diseases in open-access papers, as found by Europe PMC text mining. Sharing a sentence is not in itself a finding about the gene and the disease. The quoted sentences say what the papers report.
breast carcinoma (9 papers, 2012 to 2025). "Moreover, the TSGA10 gene could express different transcript variants with the same coding region but different 5′UTR sequences in breast cancer." (PMID 36860313, 2023). "Specially, TSGA10 expression is decreased in esophageal squamous cell carcinoma and breast cancer cells in comparison to normal controls which introduces it as a tumor suppressor gene." (PMID 39744514, 2025). "There is an association between aberrant expression of TSGA10 and different conditions such as acute myeloid leukemia (AML), acute lymphoblastic leukemia (ALL), brain tumors, breast cancers, gastrointestinal tumors, skin tumors and soft tissue tumors." (PMID 39744514, 2025). "In support, it has been demonstrated that TSGA10 overexpression in MCF-7 breast cancer cells upregulated the expression of E-cadherin, a classical biomarker of epithelial cells." (PMID 39272902, 2024). "This study demonstrates that TSGA10 transcripts in breast cancer cells tend to have shorter 5′ UTRs with fewer upstream open reading frames." (PMID 39272902, 2024). "RT-PCR of patients’ tumor samples and breast cancer cell lines were carried out using specific primers for TSGA10, PIWIL2, TEX101 and ODF3 genes." (PMID 23396665, 2012). "Expression of TSGA10 in 70% of patients with breast cancer and the presence of auto Ab against TSGA10 in 12% of patients confirmed the immune response against CT antigens in the patients." (PMID 23396665, 2012). "TSGA10 is expressed predominantly in testis and in some tumors.In our study TSGA10 expressed in 35/50 (70%) of breast cancer samples, in which 5 (10%) showed expression in the first RT-PCR, and 30 (60%) in the reamplification, semi nested PCR." (PMID 23396665, 2012). "Because of the important roles of Tsga10 in cell proliferation, we concluded that this gene may have a role in proliferation and survival of breast cancer cells and could be used for diagnosis and immunotherapy of breast cancer." (PMID 23396665, 2012). "Both of breast cancer cell lines exhibited very strong expression of TSGA10." (PMID 23396665, 2012). "We analyzed the expression of TSGA10 in breast cancer cell lines." (PMID 23396665, 2012). "In 2012, we investigated the expression of CTGs Tsga10, TEX101, and ODF3 in patients with breast cancer." (PMID 37509276, 2023). "In this study we tried to show the expression of three cancer testis genes, TSGA10, TEX101 and ODF3 in breast cancer patients as well as breast cancer cell lines." (PMID 23396665, 2012). "In conclusion, the expression of three CT antigens, TSGA10, TEX101 and ODF3 were checked in breast cancer patients." (PMID 23396665, 2012). "In this study we determined the expression of cancer testis genes Tsga10, TEX101 and ODF3 in patients with breast cancer." (PMID 23396665, 2012). "ELISA test for TSGA10 was positive in 6/50 (12%) of breast cancer patients, but it was negative in all normal control serums." (PMID 23396665, 2012). "In addition, the active expression of some testis-specific genes, including testis specific-10 (TSGA-10), testis expressed-101 (TEX101), and the outer dense fiber of sperm tails-3 (ODF-3), has already been approved in breast cancer as the cancer–testis (CT) gene." (PMID 41009526, 2025). "The negative relationship between expression of TSGA10 and HIF-α subunits was also verified in both cervical and breast cancer." (PMID 31772141, 2019). "ELISA test was performed for detection of antibody against TSGA10, TEX101 and ODF3 in serum of breast cancer patients and normal healthy controls." (PMID 23396665, 2012).
nasopharyngeal carcinoma (7 papers, 2018 to 2023). A carcinoma arising from the nasopharyngeal epithelium. "In addition, nasopharyngeal carcinoma (NPC) cell-derived exosomal miRNA-23a directly target the TSGA10 region to promote endothelial cell proliferation, migration and tube formation to regulate tumor growth." (PMID 30954079, 2019). "For instance, miR-23a, originating from nasopharyngeal carcinoma (NPC), exerts a crucial role in promoting angiogenesis by selectively targeting TSGA10." (PMID 37605155, 2023). "In nasopharyngeal carcinoma (NPC), exosomal miR-23a mediates angiogenesis by repressing TSGA10 and phosphorylation of ERK, which enhances tube generation ability of human umbilical vein endothelial cells (HUVECs) in vitro and in vivo." (PMID 32299469, 2020).
Infertility (6 papers, 2021 to 2025). "This variant was further verified by Sanger sequencing which revealed that the TSGA10 variant in the mutated patients recessively co-segregating with the infertility phenotype in this family." (PMID 38317066, 2024). "Previously, loss of function mutation in TSGA10 was reported to be associated with ASS in infertile patients." (PMID 38317066, 2024). "In sum, these predicted mutations significantly influence the function of TSGA10 and they could be used for precise study of this protein in infertility and cancer experimental investigations." (PMID 39744514, 2025). "The relative abundance in transcripts of few TH2B associated genes- CREM, CDYL, PRKAG2, CATSPERB, TSGA10 and TSSK1B was studied in sperm of fertile and infertile men with asthenozoospermia-, oligozoospermia- or oligoasthenozoospermia." (PMID 33933143, 2021). "Also, our results justify the previous reports on TSGA10 mutant infertile patient and Tsga10 knockout mouse model." (PMID 38317066, 2024). "However, the role of this protein in spermatogenesis is demonstrated previously so that deletion or mutation in the TSGA10 gene can lead to non-obstructive infertility." (PMID 39744514, 2025). "Testis specific gene antigen 10 (TSGA10) is a protein which has roles in spermatogenesis and cancers so that deletion or mutation in the TSGA10 gene resulted in non-obstructive infertility and aberrant expression of this protein, was detected in solid tumors and leukemia." (PMID 39744514, 2025). "Despite the crucial roles of TSGA10 in tumorigenesis and infertility, yet it is not obvious how various nsSNPs of its gene impress the structure and function of the TSGA10." (PMID 39744514, 2025).
esophageal squamous cell carcinoma (5 papers, 2019 to 2025). Esophageal squamous cell carcinoma (ESCC) is a type of esophageal carcinoma (EC) that can affect any part of the esophagus, but is usually located in the upper or middle third. "Hsa‐mir‐577 could play a role in the cell proliferation of esophageal squamous cell carcinomas and glioblastoma multiforme by regulating a tumor‐associated antigen, testis specific 10 28, and the Wnt signaling pathway 29, respectively." (PMID 30761256, 2019). "Low expression of TSGA10 in some high-grade tumors like nasopharyngeal carcinoma and esophageal squamous cell carcinomas was shown previously." (PMID 39744514, 2025).
male infertility (4 papers, 2021 to 2024). The inability of the male to effect fertilization of an ovum after a specified period of unprotected intercourse. "Functional analysis of the Tsga10 gene in knockout mice demonstrated that TSGA10 contribute to the correct arrangement of a mitochondrial sheath in spermatozoa, and its deficiency leads to male infertility." (PMID 37670815, 2023). "Additionally, the deficiency of the TSGA10 gene can also lead to male infertility in mice." (PMID 38891632, 2024). "Intersection of genes from transcriptomic studies with genes with identified rare variants revealed a total of 7 genes linked with male infertility phenotype (CYP11A1, CYP17A1, RSPH3, TSGA10, AKAP4, CCIN, NDNF)." (PMID 37670815, 2023). "Further investigation into the ultrastructural localizations, specific protein interactions and signaling pathways involving TSGA10 will be critical for elucidating its precise role in sperm tail assembly and function, as well as its potential contribution to male infertility." (PMID 38317066, 2024).
acephalic spermatozoa syndrome (3 papers, 2021 to 2024). "So far, the genetic etiology of TSGA10 variations have been associated with about 3.1% of reported cases suffered from acephalic spermatozoa syndrome." (PMID 38317066, 2024). "Altogether, our study identifies a novel TSGA10 pathogenic variant as a cause of acephalic spermatozoa syndrome in this family and provides information regarding the clinical manifestations associated with TSGA10 variants in human." (PMID 38317066, 2024). "Overall, all these findings provide the genetic evidence that the homozygous missense variant in TSGA10 is pathogenic for acephalic spermatozoa syndrome." (PMID 38317066, 2024). "Although loss-of-function variations in several genes, including TSGA10, have been associated with acephalic spermatozoa syndrome, the genetic cause of many cases remains unclear." (PMID 38317066, 2024). "TSGA10 defects have also been reported to cause acephalic spermatozoa syndrome." (PMID 34422805, 2021).
acute myeloid leukemia (3 papers, 2019 to 2025). Acute myeloid leukemia (AML) is a group of neoplasms arising from precursor cells committed to the myeloid cell-line differentiation. "Another study demonstrated that TSGA10 was downregulated in 93% of patients with acute myeloid leukemia (AML) compared with healthy controls." (PMID 39272902, 2024). "In acute myeloid leukemia, the interaction between TSGA10 and HIF1-α leads to a decrease in VEGF secretion." (PMID 31772141, 2019). "The prognostic value of TSGA10 is also identified in acute myeloid leukemia and transitional cell carcinoma of the bladder." (PMID 31772141, 2019).
glioblastoma (2 papers, 2019 to 2025). The most malignant astrocytic tumor (WHO grade IV). "For instance, loss of TSGA10 expression—common in tumors like glioblastoma —may unleash HIF-1α activity, locking cells into glycolysis, exacerbating ROS production (via mitochondrial uncoupling), and fostering genomic instability." (PMID 40507237, 2025). "In cancer, TSGA10’s expression is context-dependent: Its downregulation in tumors like glioblastoma might disrupt mitochondrial coupling, promoting electron leakage, ROS accumulation, and genomic instability." (PMID 40507237, 2025). "However, in a phase of cancer progression where TSGA10 is downregulated (e.g., glioblastoma), perhaps under HIF-1α pressure, disrupted coupling at Complex III may promote electron leakage, elevating ROS to mutagenic levels that drive oncogenic mutations." (PMID 40507237, 2025).
astrocytoma (1 paper, 2023). "Compared to the other tumor groups, high expressions of TSGA10 and GGNBP2 were observed in astrocytoma’s grade 2." (PMID 36860313, 2023). "Accordingly, understanding their expression levels may be informative relative to the influence of the TSGA10 and GGNBP2 genes in astrocytoma and, consequently, in patients’ prognoses." (PMID 36860313, 2023).
brain tumor (1 paper, 2023). "Public data on brain tumor microarray datasets in GEO were analyzed with R software to evaluate the expression levels of TSGA10 and GGNBP2 genes (the Pheatmap package in R was also used to plot DEGs in a heat map)." (PMID 36860313, 2023). "This article reports on the different expression patterns of TSGA10 and GGNBP2 transcript variants with different 5′UTR sequences in human brain tumor samples." (PMID 36860313, 2023). "We used RT-PCR to identify the expression pattern of TSGA10 and GGNBP2 transcript variants and the characteristics of their expression profiles in different brain tumor samples." (PMID 36860313, 2023). "Although our study showed the expression of different transcript variants of TSGA10 and GGNBP2 genes in brain tumor samples, several limitations could affect this study." (PMID 36860313, 2023). "TSGA10 and GGNBP2 gene variants expression in 30 brain tumor samples." (PMID 36860313, 2023). "In addition, to validate our in-silico data analysis, RT-PCR was performed to determine the splicing variants of TSGA10 and GGNBP2 genes in testis and brain tumor samples." (PMID 36860313, 2023). "Therefore, decreased amounts of TSGA10 and GGNBP2 as potential tumor suppressor proteins, especially in high-grade brain tumors, may cause cancer development by angiogenesis and metastasis." (PMID 36860313, 2023). "Moreover, we investigated the pathways and genes related to TSGA10 and the brain tumor." (PMID 36860313, 2023). "We identified that the TSGA10 and GGNBP2 were expressed in all of the brain tumor and testicular tissue samples, but the expression of the transcript variants with longer 5′UTR was reduced in brain tumor samples, unlike the testis sample." (PMID 36860313, 2023). "The present study undertook a microarray analysis and found that differential expression of TSGA10 and GGNBP2 were deregulated in brain tumor samples." (PMID 36860313, 2023).
ependymoma (1 paper, 2023). A WHO grade II, slow growing tumor of children and young adults, usually located intraventricularly. "In the GSE50161, the TSGA10 expression was also reduced in the ependymoma tumor with a log2 fold change of -2.67." (PMID 36860313, 2023).
Fibroadenoma (1 paper, 2012). A benign tumor of the breast characterized by the presence of stromal and epithelial elements. "No expression of TSGA10 was shown in ANCT and fibroadenoma samples." (PMID 23396665, 2012).
hepatocellular carcinoma (1 paper, 2025). A malignant tumor that arises from hepatocytes. "TSGA10 is overexpressed in cancers such as melanoma, colon cancer, hepatocellular carcinoma, ovarian cancer, prostate cancer, and leukemia." (PMID 40507237, 2025). "However, in hepatocellular carcinoma, TSGA10’s link to drug resistance via lncRNAs implies a more complex metabolic interplay, potentially involving stress-induced adaptations." (PMID 40507237, 2025).
leukemia (1 paper, 2025). A malignant (clonal) hematologic disorder, involving hematopoietic stem cells and characterized by the presence of primitive or atypical myeloid or lymphoid cells in the bone marrow and the blood. "Additionally, aberrant expression of TSGA10, was detected in solid tumors and leukemia in several studies." (PMID 39744514, 2025).
medulloblastoma (1 paper, 2023). A malignant, invasive embryonal neoplasm arising from the cerebellum. "Higher-grade BTs display a sharp decrease in TSGA10 and GGNBP2 transcripts, especially in medulloblastoma grade IV, given that TSGA10 and GGNBP2 expressions decrease in higher grades of BTs." (PMID 36860313, 2023).
sterility (1 paper, 2022). "Five genes (Tsga10, Terb1, Stra8, Tex14, and Spam1) were predicted to be associated with sterility in male and female Mule ducks." (PMID 36386800, 2022).
systemic lupus erythematosus (1 paper, 2023). An autoimmune multi-organ disease typically associated with vasculopathy and autoantibody production.
testicular tumors (1 paper, 2025). "Notably, TSGA10’s role in thermoregulation could also explain why certain cancers thrive in thermally unstable niches (e.g., testicular tumors), where disrupted TSGA10-HIF-1α feedback loops might permit metabolic plasticity." (PMID 40507237, 2025).